APOE (apolipoprotein E)
Diseases named in the same sentence as APOE in open-access papers (continued):
Sharing a sentence is not in itself a finding about the gene and the disease.
Alzheimer disease (continued). "LACTB2 and PLIN2 had novel significant associations with Alzheimer’s disease and BIN1, PTK2B, SPI1, MS4A4A, MS4A6E, APOE and PVR are in known Alzheimer’s disease risk loci from GWAS." (PMID 33959712, 2021). "Apolipoproteins C-I, C-II, and C-III interact with ApoE to regulate lipoprotein metabolism and contribute to Alzheimer's disease pathophysiology." (PMID 33518512, 2021). "The contributions of TREM2 and APOE to neurological diseases [e.g., Alzheimer’s disease (AD) or multiple sclerosis (MS)] have been extensively described with regard to MG." (PMID 34539650, 2021). "One study in humans observed a gene dose-dependent effect of APOE ε4 on dendritic spine density among Alzheimer’s disease patients and found that among cognitively normal individuals, ε4 carriers had fewer spines than noncarriers." (PMID 34071923, 2021). "The apolipoprotein E (APOE) genotype is an established risk factor for cardiovascular disease (CVD), neuropathology, and Alzheimer’s disease." (PMID 34836179, 2021). "In conclusion, we provide novel preliminarily evidence that the APOE genotype modifies DHA associations with brain volume and spatial navigation ability, typically affected in the first stages of Alzheimer’s disease." (PMID 34007965, 2021). "Ethical and regulatory implications must be considered when providing APOE nutrigenetic tests given the well-established link between APOE genetic variation and Alzheimer's Disease." (PMID 35237638, 2021). "Apolipoprotein E (APOE) genotype, the strongest genetic risk factor for late onset Alzheimer disease (AD), is determined by the combination of amino acids at positions at 112 and 158 yielding three common alleles (ε2, ε3, and ε4)." (PMID 34480088, 2021). "This, in fact, is in line with results from this study, as we found that APOE-by-sex interaction affects Alzheimer’s disease patients in a relatively early disease stage (Braak I–II)." (PMID 34189460, 2021). "One such emerging target is apolipoprotein E (APOE), identified nearly 30 years ago as one of the strongest and most reproduceable genetic risk factor for late-onset Alzheimer’s disease (LOAD)." (PMID 33513969, 2021). "For example, it transactivates Apolipoprotein E (APOE), which is associated with the metabolism of fats and Alzheimer's disease." (PMID 33538087, 2021). "Most studies on ApoE have focused on cardiovascular disease and Alzheimer’s disease risks due to its role related to lipids." (PMID 34867826, 2021). "Previous studies have revealed that the APOE ε4 allele is an established genetic risk factor for coronary heart disease (CHD), atherosclerosis and Alzheimer’s disease and influences the development of CHD." (PMID 34587962, 2021). "Brain fibrinogen level was also raised in Alzheimer’s disease in individuals homozygous for APOE ε4, as was EDN1 level (Supplementary)." (PMID 33723589, 2021). "Excluding variants from in and around the APOE locus led to a marked attenuation of the relationship between genetic instruments for apoB and LDL cholesterol and risk of Alzheimer’s disease in mothers." (PMID 34729547, 2021). "The biomarker of amyloid peptide and the Alzheimer's disease risk (BALTAZAR) study found that the plasma Aβ was associated with cognitive performance, apolipoprotein E (APOE)-ε4 status, and CSF Aβ in cross-sectional analyses." (PMID 33716709, 2021). "The distinct mechanisms by which each apoE isoform influences myeloid cell functions are reminiscent of isoform-specific differences in signaling pathways in neurons that affect Alzheimer’s disease." (PMID 34425108, 2021).
Alzheimer disease (continued). "Using the EPIC array, we investigated epigenome-wide differences in whole blood DNA methylation patterns between Alzheimer’s disease-free APOE ε4 (n = 2469) and ε2 (n = 1118) carriers from the two largest single-cohort DNA methylation samples profiled to date." (PMID 33397400, 2021). "In patients with Alzheimer’s disease, APOE ε4 carrier was discovered to lead to a significantly faster disease progression." (PMID 34587962, 2021). "These patterns were accentuated in APOE Ɛ4 allele carriers, suggesting an association between APOE4 genotype and Alzheimer's disease pathology with apoCs processing and function in the brain." (PMID 33518512, 2021). "Here, the authors show that specific isoforms of the phospholipid forming APOE lipoproteins activate microglia in pre-clinical mouse models of Alzheimer’s disease." (PMID 34099706, 2021). "Specifically, apolipoprotein E of astrocytic origin causes an increase in BBB permeability associated with age and Alzheimer’s disease due to the pro-inflammatory effects of cyclophilin and the activation of matrix metalloproteinase MMP-9." (PMID 34796023, 2021). "Association of APOE, EGFR, and ACTB SNPs with Alzheimer’s disease under logistic regression analysis." (PMID 34956307, 2021). "Contextually, this somewhat resembles the roles of the APOE genotypes in Alzheimer's disease (AD) and vascular dementia (VaD)." (PMID 34512528, 2021). "The most frequent reports in the literature are on the role of ApoE expression in the formation and development of Alzheimer’s disease, also in the context of changes in the profile and degree of its glycosylation." (PMID 34281251, 2021). "For example, the apolipoprotein E (APOE), highly associated with LOAD risk, has been found to be strongly associated with memory in healthy adults before the clinical manifestation of Alzheimer’s disease." (PMID 34386032, 2021). "Mice with targeted replacement of human APOE2, APOE3, and APOE4 (APOE-TR mice) have been widely used to study the role of APOE4 in Alzheimer’s disease." (PMID 33822768, 2021). "The apolipoprotein E4 (APOE4) allele is considered a major shared risk factor for both cardiovascular disease (CVD) and Alzheimer’s disease (AD), in part due to its role in lipid metabolism and related inflammation." (PMID 34586066, 2021). "Since apoE first gained notoriety as a genetic marker for Alzheimer’s disease (AD), an extensive body of literature has investigated the impact of the apoE isoforms in the brain." (PMID 33536234, 2021). "Sex-related difference in Alzheimer’s disease (AD) has been proposed, and apolipoprotein E (ApoE) isoforms have been suggested to be involved in the pathogenesis of AD." (PMID 33746700, 2021). "We examined the impact of an APOE ε4 genotype on Alzheimer's disease (AD) subject platelet and lymphocyte metabolism." (PMID 33939248, 2021). "In the last years, a gene–environment interaction (GxE) between APOE and PA in Alzheimer’s disease (AD) has been suggested." (PMID 32110803, 2020). "Investigations of apolipoprotein E (APOE) gene, the major genetic risk modifier for Alzheimer’s disease (AD), have yielded significant insights into the pathogenic mechanism." (PMID 33148290, 2020). "Although APOE ɛ4 and genetic scores for late-onset Alzheimer’s disease (LOAD) have been related to cognitive decline during preclinical stages of dementia, there is limited knowledge concerning genetic factors implied in normal cognitive aging." (PMID 32709845, 2020). "ApoE has been shown to play integral roles in overall brain health and impact the development of Alzheimer’s disease." (PMID 32425941, 2020). "The chromosome 19 locus includes the apolipoprotein gene cluster (including APOE), which has been the focus of much research into lipid levels, cardiovascular disease, and Alzheimer disease." (PMID 31801372, 2020).
Alzheimer disease (continued). "Adding PHS to the model that uses APOE burden led only to statistically significant improvement for the CN versus Alzheimer’s disease classification (AUC increased from 0.765 to 0.777; P < 0.006)." (PMID 32226939, 2020). "The results showed that the sensitivity of APOE genotype in the diagnosis of Alzheimer's disease was 0.62 (0.58-0.66), the specificity was 0.84 (0.81-0.86), and the area under the SROC curve was 0.80 (0.76-0.83)." (PMID 33101544, 2020). "These reductions were significant with FC for 5 genes critical to Alzheimer’s disease (AD): Apbb1, ApoE, Mapt (Tau), Psen1, and Prnp." (PMID 32561719, 2020). "Our findings indicate the possible roles of apoE and TNF‐α in the pathogenesis of APOE‐ε4‐associated Alzheimer's disease." (PMID 32426945, 2020). "EXOC3L2 has not been previously reported to modulate dyslipidemia but EXOC3L2, APOE, TOMM40, and PVRL2 are reported to be Alzheimer’s disease-susceptibility genes." (PMID 32727492, 2020). "APOE genotypes and polygenic genetic burdens for Alzheimer’s disease, Parkinson’s disease, and frontotemporal dementia were obtained through genome-wide genotyping." (PMID 32116848, 2020). "A working model, attempting to explain the relationship between ApoE and Alzheimer’s disease, has been proposed." (PMID 32325882, 2020). "Our findings show the APOE independent Alzheimer’s disease PGS can be successfully implemented in population-based research of a broad dementia phenotype." (PMID 33143703, 2020). "Another disease that has been prioritized by multiple studies is Alzheimer’s disease, for which models consistently prioritize APOE." (PMID 32351543, 2020). "The presence of APOE ε4 significantly influences the progression of healthy elderly to MCI and Alzheimer disease, and the progression risk peaks between ages 70 and 75 years." (PMID 32379048, 2020). "The Apolipoprotein E (APOE) e4 allele is associated with reduced longevity and increased Coronary Artery Disease (CAD) and Alzheimer’s disease, with e4e4 having markedly larger effect sizes than e3e4." (PMID 32511104, 2020). "Another study identified specific CR1 SNPs (rs6656401 and rs4844609) that influenced rate of cognitive decline in Alzheimer’s disease in combination with APOE status." (PMID 32907542, 2020). "Previous studies have shown evidence for plausible links of apolipoprotein E (APOE), the most important genetic marker for Alzheimer’s disease, with early-life cognition and neuroimaging markers." (PMID 32116848, 2020). "With respect to the LDL receptor pathway, apolipoprotein E (ApoE), which binds with high affinity to the LDL receptor, is associated with Alzheimer disease (AD) and altered neurosteroid levels (described in detail below)." (PMID 32756865, 2020). "APOE ε4 canmodify the prevalence and incidence of late-onset Alzheimer’s disease (LOAD), inaddition to the cognitive performance in affected carriers." (PMID 32973976, 2020). "There are three major alleles of the APOE gene (APOE2, APOE3, and APOE4), all of which have consistently demonstrated their roles in risk of cardiovascular disease (CVD) and Alzheimer’s disease (AD)." (PMID 33065985, 2020). "The apolipoprotein E gene (APOE) ε4 allele is the strongest genetic risk factor for dementia and Alzheimer’s disease identified to date (Bettens, Sleegers, & Van Broeckhoven, 2013)." (PMID 32772803, 2020). "The triggering receptor expressed on myeloid cells 2 (TREM2)/apolipoprotein E (APOE) pathway has been in the focus of microglia analysis since it was shown that this pathway is important during Alzheimer’s disease progression as well as during EAE/MS." (PMID 33058309, 2020). "The importance of apolipoprotein E (APOE) in late-onset Alzheimer's disease (LOAD) has been firmly established, but the mechanisms through which it exerts its pathogenic effects remain elusive." (PMID 32859588, 2020).
Alzheimer disease (continued). "Apolipoprotein E (APOE) variants have been established as a strong risk factor for cardiovascular disease and Alzheimer’s disease and are associated with altered LDL-C levels." (PMID 32697195, 2020). "For example, in Alzheimer’s disease (AD), APOE4 (apolipoprotein E) is the major genetic risk factor." (PMID 33003360, 2020). "Genetically, Apolipoprotein E (APOE) ε4 has been shown to occur less commonly in PART than in Alzheimer’s disease (AD)." (PMID 33287896, 2020). "MDD: Major Depressive Disorder; CAD: coronary artery disease; AD: Alzheimer’s Disease (excluding APOE locus; *for the full autosomal reference panel, i.e., including APOE, hl2=0." (PMID 32427991, 2020). "Selection of preclinical and clinical evidence supporting the role of apolipoprotein E (apoE) in protecting from Alzheimer’s disease (AD)." (PMID 33287338, 2020). "Here we sought to identify genetic associations between POAG and variants in APOE and TREM2, genes associated with Alzheimer disease (AD) that critically regulate microglial neurodegeneration-associated molecular signature." (PMID 32614373, 2020). "Apolipoprotein E (APOE) was suggested to play a role in late onset Alzheimer’s disease (LOAD), the sporadic form of AD, long before GWAS era." (PMID 33152005, 2020). "APOE is a lipoprotein whose primary function is transporting cholesterol, but it also controls the formation of protein aggregates in Alzheimer disease (AD) through the regulation of amyloid‐β (Aβ) metabolism, aggregation, and deposition." (PMID 32749065, 2020). "Apolipoprotein E (APOE) ε4 gene allele and type 2 diabetes mellitus (T2DM) are prime risk factors for Alzheimer’s disease (AD)." (PMID 32075060, 2020). "Preclinical models of Alzheimer’s disease (AD) suggest APOE modulates brain function in structures vulnerable to AD pathophysiology." (PMID 31896120, 2020). "Consistently, both carrier status of Apolipoprotein E ε4 allele (APOE4), and age-related aggregation of Alzheimer’s disease (AD) pathology result in altered brain network connectivity." (PMID 32210782, 2020). "The ε4 allele of apolipoprotein E (APOE) gene (APOE4) and increasing age are two of the most important known risk factors for developing Alzheimer disease (AD)." (PMID 32817639, 2020). "Removal of APOE not only impairs cognitive functions but also reduces neuritic amyloid plaques in mouse models of Alzheimer’s disease (AD)." (PMID 30760557, 2019). "One such marker is the apolipoprotein E (APOE) ε4 allele, which is a well-known genetic risk factor for Alzheimer’s disease." (PMID 31798373, 2019). "While the ApoE ε4 allele is a known risk factor for mild cognitive impairment (MCI) and Alzheimer's disease, brain region specific effects remain elusive." (PMID 30991617, 2019). "The effects of ApoE in Alzheimer's disease have long been studied but by comparison the study of the related apolipoprotein clusterin has been limited despite it too being a genetic risk factor for the disease." (PMID 31853523, 2019). "Apolipoprotein E4 (ApoE4) is found in 25% of the population, and in 60% of Alzheimer’s disease (AD) patients." (PMID 31280254, 2019). "Theoretical background: The Apolipoprotein E (APOE) ε4 genotype is known to be one of the strongest single-gene predictors for Alzheimer disease, which is characterized by widespread brain structural degeneration progressing along with cognitive impairment." (PMID 31191441, 2019). "The neuritic plaque is the single point at which many of the key features of Alzheimer’s disease pathophysiology converge: amyloid-β, tau, microglia and APOE and therefore it seems likely to represent a key component of the evolution of the disease process." (PMID 31157360, 2019). "This methodology was later applied in an immunosensor using CdSe@ZnS QDs tags for the detection of apolipoprotein E (ApoE), an Alzheimer’s disease biomarker, at clinical relevant levels of ng/mL." (PMID 31771201, 2019).
Alzheimer disease (continued). "In Alzheimer’s disease, ApoE interactions with molecules important for lipid efflux and lipid endocytosis underlie effects of ApoE genotype on neuroinflammation and lipoprotein composition." (PMID 31788012, 2019). "Estimate of the main effect of single-nucleotide polymorphisms (SNPs) (γG)^ and their interaction effect with ApoE ε4 status in the Alzheimer disease study." (PMID 31681402, 2019). "For instance, a case-control study has shown that people with Alzheimer’s disease have greater renal impairment than controls, even after adjustment for age, diastolic blood pressure, apolipoprotein E (APOE) ɛ4 genotype and education level." (PMID 31474869, 2019). "By age 85, the lifetime risk estimate of developing Alzheimer's Disease Dementia (ADD) is 60–70% for ε4/ε4 homozygotes and 20–30% for ε4/ε3 heterozygotes (ApoE carriers)." (PMID 30991617, 2019). "In Alzheimer's disease, different isoforms of ApoE play different roles in the pathogenesis of amyloidosis: ApoE4 has been shown to promote or inhibit the assembly of Aβ protein into filaments in both in vitro and in vivo mouse models." (PMID 31281565, 2019). "Combining the use of magnetic bead platforms and IrO2 NPs as labels of antibodies, they applied this catalytic method for the detection of ApoE, an Alzheimer’s disease biomarker at ng/mL levels." (PMID 31771201, 2019). "The APOE ε4 allele has been consistently linked to normal cognitive decline in MCI and AD dementia patients." (PMID 31680923, 2019). "We found two lifespan candidate loci which were previously associated with Alzheimer’s disease: the newly identified EPHX2/CLU and, perhaps the most widely reported candidate lifespan locus: APOE." (PMID 31484785, 2019). "Oestrogens-ApoE interactions are suggested to be involved in other neurological conditions with a sex bias and abnormal cholesterol metabolism, such as Alzheimer disease." (PMID 30787904, 2019). "One genetic factor that is attracting increasing attention is the Apolipoprotein E (APOE) genotype, which has been linked to Alzheimer’s disease." (PMID 31694658, 2019). "Although not as mainstream as amyloid and tau approaches, there are approaches for targeting apoE in Alzheimer’s disease being undertaken in academia and industry." (PMID 31052389, 2019). "Considering the evidence for genetic associations of Alzheimer’s disease and WMH burden, and relationships between ApoE and Alzheimer’s disease, we elected to extend our earlier, null result, candidate gene study to include promoter regions of the ApoE gene." (PMID 31551090, 2019). "Genetic factors that influence Alzheimer’s disease (AD) risk include mutations in TREM2 and allelic variants of Apolipoprotein E, influencing AD pathology in the general population and in Down syndrome (DS)." (PMID 30909239, 2019). "Alzheimer’s disease PRS based on AD-associated SNPs, excluding the APOE region, was used to predict Ch4 volume in normal control subjects." (PMID 31354783, 2019). "Alzheimer’s disease PRS based on AD-associated SNPs, excluding the APOE region, was used to predict Ch4 volume in AD patients using linear regression." (PMID 31354783, 2019). "Sixty-five β-amyloid-positive patients at the prodromal and dementia stages of Alzheimer’s disease were enrolled, including APOE ε4-positive (n = 46) and APOE ε4-negative (n = 19) patients." (PMID 30086796, 2018). "In view of this, numerous mechanisms have been postulated to elucidate the influence of apolipoprotein E in Alzheimer’s disease patients’ brain." (PMID 30097809, 2018). "Using cognitive data, hippocampal volume, APOE ε4 genotype and peripheral blood protein markers from the Alzheimer’s Disease Neuroimaging Initiative (ADNI) dataset, they obtained AUC = 0.80 for predicting amyloid pathology in subjects with MCI." (PMID 30261928, 2018). "ApoE is well known as one of the key molecules involved in Alzheimer’s disease and other neurological disorders." (PMID 29357368, 2018).